INS (insulin)
Diseases named in the same sentence as INS in open-access papers (continued):
Sharing a sentence is not in itself a finding about the gene and the disease.
type 2 diabetes (continued). "In this study, we performed a two-sample MR study to examine whether insomnia, sleep duration, short sleep duration, body fat percentage, VAT accumulation, type 2 diabetes mellitus (T2DM), fasting glucose, and fasting insulin were causally associated with the risk of GERD." (PMID 36895273, 2023). "The worldwide increase in obesity, type-2 diabetes, non-alcoholic liver disease, and cardiovascular diseases has stimulated interest in identifying dietary constituents capable of controlling blood glucose, insulin, and lipids as well as blood pressure, and food intake." (PMID 36832775, 2023). "While it is likely that some individuals in this group will not require insulin and may benefit from adjuvant (type 2 diabetes-associated) agents, clinical studies are limited." (PMID 37728732, 2023). "Type 2 diabetes (T2DM) is a chronic metabolic disease that primarily manifests as hyperglycemia due to impaired insulin secretion and/or action resulting from various etiologies." (PMID 37600949, 2023). "Therefore, patients with type 2 diabetes should be treated to improve relevant glucose and insulin indices then, appropriate hypoglycemic drugs should be selected in combination with their economic status and family background, to improve the pertinent treatment." (PMID 36755915, 2023). "Type 2 diabetes (T2DM) is one of the most common metabolic disorders worldwide, which is caused by a combination of two main factors: defective insulin secretion by pancreatic beta cells and the inability of insulin-sensitive tissues to respond appropriately to insulin." (PMID 37274326, 2023). "Insulin-resistant women with PCOS produce insulin and regulate their blood glucose levels; however, the body fails to respond to insulin efficiently and this may ultimately result in impaired glucose tolerance and type 2 diabetes." (PMID 37510690, 2023). "Type 2 diabetes (T2D) is a complex metabolic disease, which involves maintained hyperglycemia, mainly due to the development of an insulin resistance process." (PMID 37111688, 2023). "Recently, a P28 to leucine mutation has been reported in a case of maturity-onset diabetes of the young (MODY) presenting defects in PI folding, trafficking and dominant-negative behavior in vitro, emphasizing the clinical importance of cis–trans isomerization in insulin biosynthesis." (PMID 36671537, 2023). "Type 2 diabetes mellitus (T2DM) is a chronic and systemic metabolic disease characterized by resistance to insulin or insufficient production of it." (PMID 36694151, 2023). "For patients with type 2 diabetes (T2D), achieving recommended glycemic targets remains difficult, especially in people treated with basal insulin." (PMID 36749650, 2023). "Moreover, a number of studies on dynapenia and type 2 diabetes further support the relevance of metabolic derangements related to insulin sensitivity and glucose tolerance in the decline of muscle strength, especially when dynapenia is coupled with abdominal obesity." (PMID 36831008, 2023). "The use of this GIP/GLP-1 dual agonist in individuals with type 2 diabetes has shown superiority with respect to HbA1c lowering, body-weight reduction, improvement in lipid profile and reduction of arterial blood pressure, as compared with placebo, semaglutide or insulin." (PMID 37542009, 2023). "In addition to fiber intake, protein and lipid preloading have been found to control postprandial glycemic elevation in people with type 2 diabetes and in healthy individuals by promoting insulin, glucagon-like peptide-1 (GLP-1), and gastric inhibitory peptide secretion." (PMID 37299565, 2023). "In spite of abundant evidence demonstrating that in type 2 diabetes early glycemic control is correlated with a reduction in long‐term complications, data from many health systems indicate that delay in initiation and/or intensification of insulin therapy remains systemic." (PMID 36889912, 2023).
type 2 diabetes (continued). "Considering the critical role of inflammation in the development of insulin resistance and Type 2 Diabetes Mellitus (T2DM), a body of research investigating the role of insulin dysregulation in AD has emerged." (PMID 37426432, 2023). "Moreover, pancreatic insulin:proinsulin ratio, a measure of the efficiency of proinsulin processing to insulin that is perturbed in β-cells of type 2 diabetics, was increased in db/db mice treated with the highest, 1 mg/g, dose of O304 compared with untreated db/db mice." (PMID 37626210, 2023). "When oral hypoglycemic drugs fail to control blood glucose in patients with type 2 diabetes (T2DM), these patients typically begin using insulin." (PMID 38027146, 2023). "Type 2 diabetes mellitus (T2DM) is a complex metabolic disorder recognized with impaired insulin secretion, insulin resistance, and hyperglycemia manifestations caused by the defects in pancreatic b-cells." (PMID 36703777, 2023). "The benefits of real-time continuous glucose monitoring (RT-CGM) are well established for patients with type 1 diabetes (T1D) and patients with insulin-treated type 2 diabetes (T2D)." (PMID 36602920, 2023). "Interestingly, we observed that patients with cancer had a significantly higher risk of developing type 2 diabetes and insulin treatment than those without during a 10-year follow-up period." (PMID 36831436, 2023). "The type-II diabetes model is better than a type-I diabetes model because wound infection along with severe hyperglycemia may lead to more mortality among the animals unless these animals are injected with insulin to maintain their blood glucose levels." (PMID 36985266, 2023). "Estrogen protects against type 2 diabetes in women in trials, mainly through activating estrogen receptor α in various tissues (e.g. brain, liver, skeletal muscle, adipose tissue and pancreatic beta cells) and thereby improving adiposity, insulin sensitivity and glucose tolerance." (PMID 36624450, 2023). "Also, for the interpretation of insulin, it is important to take into account a interdependency of glucose and insulin during the progression of type 2 diabetes: Early in classical metabolic disease, insulin secretion is increased to ensure glucose uptake into peripheral tissues and glycogenesis." (PMID 36895000, 2023). "This study aimed to investigate the effectiveness and safety of a weight-based and ratio of 1:1.5 basal-bolus insulin using an algorithm for both initiation and titration in hospitalized patients with type 2 diabetes (T2D)." (PMID 38008775, 2023). "Dipeptidyl peptidase-4 (DPP4) deactivates incretin hormones, whereas DPP4 inhibitors, such as sitagliptin, block this degradation, increase the incretin levels, and prolong insulin secretion; therefore, sitagliptin could be a potential therapeutic for type 2 diabetes mellitus." (PMID 37047505, 2023). "Instead, adhering to a low-inflammatory diet may improve long-term hyperglycemia, metabolic disturbances, lipid profile, body composition, blood pressure, insulin sensitivity, and β-cell function, which all play important roles in the development of type 2 diabetes." (PMID 38049803, 2023). "Type 2 diabetes mellitus (T2DM) is a metabolic disorder characterized by high serum glycemic levels either due to insufficient insulin levels, defective function, or both." (PMID 36229741, 2023). "In addition, we aimed to explore differences between healthy individuals and patients with diabetes type 2, as their responses to insulin and conditioning might differ because of insulin resistance or different baseline levels of glucose or metabolic hormones." (PMID 37234022, 2023). "Improvements in glucose tolerance and insulin sensitivity have also been observed in overweight individuals with type 2 diabetes mellitus (T2D) when a single bout of aerobic exercise was performed under moderate hypoxia (i.e., ~ 3000 m)." (PMID 36441492, 2023).
type 2 diabetes (continued). "Approximately 6.3% of the worldwide population is affected by Type 2 Diabetes (T2D) with an increasing number of people on insulin therapy because of disease progression." (PMID 36983941, 2023). "Type 2 diabetes mellitus (T2DM) is a chronic metabolic disorder characterized by high levels of glucose in the blood due to the body’s inability to effectively use insulin." (PMID 37764710, 2023). "Type 2 diabetes mellitus (T2DM) is a chronic disease characterized by reduced insulin sensitivity, which results in the inability to maintain glucose homeostasis." (PMID 37404062, 2023). "Type 2 diabetes mellitus (T2DM) is a prevalent metabolic condition characterized by insulin resistance and inadequate insulin production as a result of a decline in pancreatic beta-cell activity." (PMID 37096236, 2023). "However, prolonged demand for elevated levels of circulating insulin may eventually result in β cell exhaustion, progressive β cell dysfunction, and development of type 2 diabetes (T2D)." (PMID 36574297, 2023). "It has been argued that individuals with type 2 diabetes, who have well-characterised reductions in beta cell mass and function, may already secrete insulin maximally with the weaker stimulus so that the secretory response cannot be augmented further with a stronger stimulus." (PMID 37430117, 2023). "However, the evidence that higher childhood BMI has a protective effect on measures of insulin secretion and sensitivity was not reflected in a conclusive association with protection from type 2 diabetes." (PMID 37280435, 2023). "The inability of the β-cells to release enough insulin to lower blood glucose results in development of type 2 diabetes (T2D)." (PMID 36869830, 2023). "The risk of hypoglycemia is a barrier to the optimal glucose control in the treatment of both type 1 (T1DM) and type 2 diabetes mellitus (T2DM), especially in the context of insulin therapy." (PMID 38001509, 2023). "The present study investigated the ability of liposomal berberine (Lip-BBR) to aid in ameliorating hepatic damage and steatosis, insulin homeostasis, and regulating lipid metabolism in type 2 diabetes (T2DM) and the possible pathways by which it does so." (PMID 37371950, 2023). "Type 2 diabetes mellitus (T2DM) is a metabolic disorder characterized by chronically increased blood glucose, insulin, and the dysfunction of pancreatic β-cells." (PMID 37894660, 2023). "hIAPP is co-secreted with insulin from pancreatic β cells, and due to its ability to aggregate into pancreatic islet cells in type 2 diabetes mellitus (T2DM) so-called hIAPP." (PMID 37173803, 2023). "Furthermore, flavonols may help prevent and manage type 2 diabetes by enhancing insulin sensitivity and decreasing inflammation." (PMID 37216013, 2023). "However, in patients with type 2 diabetes, the glucose concentration in the cerebrospinal fluid was lower than in normoglycemic persons, which may be because systemic insulin resistance induced intracerebral insulin resistance." (PMID 36834911, 2023). "The most common diabetes form, type 2 diabetes (T2D), affecting 462 million people globally, is characterized by the insulin resistance of peripheral tissues and (subsequent) β-cell dysfunction, exhaustion, and loss." (PMID 36899834, 2023). "Increased insulin sensitivity may be a more effective approach to controlling type 2 diabetes." (PMID 37047820, 2023). "However, fasting and glucagon-stimulated C-peptide levels did not predict responsiveness to metformin, nor did random C-peptide testing predict responsiveness to combination of metformin and a sulfonylurea when added to insulin-treated patients with type 2 diabetes." (PMID 37589043, 2023). "Additionally, both type 1 and type 2 diabetes have been linked to an elevated risk of osteoporotic fractures, attributed to the absence of bone anabolic effects of insulin or potential impairment of bone quality due to antidiabetic drugs." (PMID 37780632, 2023).
type 2 diabetes (continued). "Consequently, less than 0.1% of type 2 diabetics use insulin pump technology." (PMID 37760895, 2023). "Additionally, insulin therapy may be necessary for individuals with type 1 diabetes and those with type 2 diabetes who cannot achieve target blood sugar levels with oral medications alone." (PMID 38022307, 2023). "Moreover, histopathological staining results showed that HFD/STZ‐induced islet and pancreas were damaged in type 2 diabetic mice, which could result in impaired insulin secretion, leading to the occurrence of hyperglycemia." (PMID 38107122, 2023). "Several animal studies have demonstrated that resveratrol can prevent type 2 diabetes mellitus (T2DM), improve glucose metabolism, and enhance insulin sensitivity." (PMID 37630770, 2023). "It is not yet clear whether individuals with type 2 diabetes who are more insulin-resistant or who have a relative deficiency in insulin production are more closely associated with hypertension and dyslipidaemia." (PMID 37274075, 2023). "Moreover, because intranasal insulin normalizes hypothalamic neuronal activity in response to glucose ingestion, it could be especially favorable for type 2 diabetes patients who demonstrate distorted brain responses to glucose." (PMID 37234022, 2023). "Pharmacotherapy, including renal sodium/glucose cotransporter-2 inhibitors (SGLT2i), that can improve glycemic control when combined with insulin therapy could mitigate metabolic stress due to nutritional intake and confer additional benefits on health outcomes in type 2 diabetes." (PMID 36804863, 2023). "Type 2 diabetes mellitus (T2DM) is a metabolic disorder characterized by hyperglycaemia due to peripheral insulin resistance and inadequate insulin secretion by pancreatic beta cells." (PMID 37403240, 2023). "Furthermore, SeapolynolTM improved insulin sensitivity in type 2 diabetes and may play an important role in the prevention of metabolic diseases These tests, however, were carried out only on mice." (PMID 37367648, 2023). "Moreover, both dietary and supplementary were associated with an increased incidence of type 2 diabetes without effecting several glycemic indices including insulin level, fasting plasma glucose, and hemoglobin A1c." (PMID 37781125, 2023). "Here we proposed that fully closed-loop insulin delivery in people with type 2 diabetes may improve glycemic control compared with standard insulin therapy, without increasing the risk of hypoglycemia over an 8-week period of unrestricted living." (PMID 36631592, 2023). "The reporting of cardiovascular complications for the comparison of combining metformin with insulin compared with insulin monotherapy in people with type 2 diabetes was infrequent, and when meta-analyses could be performed, the data were sparse and effect estimates were non-significant." (PMID 36923108, 2023). "Moreover, inhibition of VEGFB expression could prevent the progression of type 2 diabetes and restore insulin sensitivity in mice fed a high-fat diet." (PMID 36875456, 2023). "Pioglitazone, a potent and selective PPAR-γ agonist, can improve insulin sensitivity and enhance hyperglycemia; thus, it has been widely used for treatment on type 2 diabetes mellitus (T2DM)." (PMID 37881366, 2023). "Despite the availability of a range of antidiabetic therapies, many people with type 2 diabetes (T2D) require insulin treatment at some stage in their disease management." (PMID 37835008, 2023). "In several preclinical studies of obesity and type 2 diabetes, higher relative abundance of Enterorhabdus was positively correlated with body weight, weight gain percentage, and fat mass accumulation as well as with blood lipids, glucose, and insulin resistance." (PMID 36892893, 2023).
type 2 diabetes (continued). "However, under the sustained hyperglycemic conditions that occur in type 2 diabetes, the continual demands of insulin production lead to glucotoxicity and apoptosis of beta cells (and possibly other islet cell types)—further exacerbating the type 2 diabetes condition." (PMID 37333221, 2023). "The lowest risk of hypoglycemia and insulin-sensitizing effect seen with pioglitazone makes it an attractive option for treating elderly type 2 diabetes patients, regardless of whether they are combined with new-generation OHA." (PMID 37036483, 2023). "Type 2 diabetes mellitus (T2DM) is a metabolic disorder characterized by fasting and postprandial hyperglycemia as well as relative insulin insensitivity." (PMID 37734909, 2023). "We found significant genetic correlations of VAT with type 2 diabetes and HbA1c, but not FG, 2hGlu or fasting insulin, suggesting that VAT accumulation might be associated with persistent dysglycaemia." (PMID 37540242, 2023). "Furthermore, as the acute inhibitory effect insulin has on TRL production under the postprandial condition is reduced in type 2 diabetes, the extent and duration of elevated postprandial HTG should be significantly increased in DM patients compared to those without DM." (PMID 37138333, 2023). "However, recent findings strongly demonstrate that defective insulin secretion may be an instigating factor in Type 2 Diabetes diseases progression." (PMID 37512508, 2023). "Type 2 diabetes mellitus (T2DM) is a complex disorder that results from several pathophysiological complications including decreased insulin secretion, increased glucose production in the liver, and increased insulin resistance." (PMID 36881587, 2023). "Therefore, our study aimed to demonstrate whether IAs or IA subclasses induced by exogenous insulin affected metabolic control and predicted adverse events in Chinese type 2 diabetic patients receiving insulin treatment." (PMID 37143729, 2023). "Different meta-analyses have demonstrated that TZP is more effective compared to insulin and GLP-1RA in decreasing weight and lowering glycemia, and does not increase the cardiovascular risk or the risk of adverse events, promising a new approach for the management of type 2 diabetes." (PMID 37779743, 2023). "Insulin resistance (IR), referred to as resistance to insulin-stimulated glucose uptake, is an essential feature of aging, vascular disease, obesity, type 2 diabetes mellitus (T2D), dyslipidemia, and other components of the metabolic syndrome." (PMID 38130393, 2023). "Some proinsulin is secreted into the plasma during insulin biosynthesis and secretion, and circulating levels of proinsulin relative to insulin are increased in individuals with type 2 diabetes (T2D) and pre-diabetes." (PMID 36693378, 2023). "Many patients with type 2 diabetes might not have a complete loss of insulin secretion, and some might have excessive insulin secretion." (PMID 36755915, 2023). "Consequently, insulin levels may elucidate the elevated BMD levels observed in individuals with type 2 diabetes." (PMID 37782659, 2023). "Interestingly, Metformin, a hypoglycemic drug used to treat diabetic patients, rescued AQP7 expression to induce insulin secretion in the rat in vitro and in vivo models of type 2 diabetes by suppressing the Mitogen-Activated Protein Kinase p38 and c-Jun N-terminal kinase (JNK) pathway." (PMID 37681902, 2023). "It was found earlier, that the PDK4 inhibition may alleviate some symptoms of type 2 diabetes in mice; in particular, PDK4 deficiency was found to decrease blood glucose and improved glucose tolerance and insulin sensiti-vity in mice with diet-induced obesity (Jeoung and Harris, 2008)." (PMID 38234967, 2023). "Type 2 diabetes mellitus (T2DM) is one of the most prevalent multifactorial chronic disorders, characterized by impaired glucose tolerance and insulin sensitivity, leading to hyperglycemia in both fasting and postprandial states." (PMID 36980809, 2023).